OR5H15 (olfactory receptor family 5 subfamily H member 15)
Description:
Odorant receptor.
Tractability: Antibody: UniProt places it where antibodies can reach, with medium confidence; UniProt predicts a signal peptide or a membrane-spanning region; its Gene Ontology location is reachable by antibodies, with medium confidence.
Gene: Protein-coding gene on chromosome 3 (98,166,696 to 98,169,774, forward strand). Ensembl gene ENSG00000233412.
Subcellular location: Cell membrane
Pathways (Reactome):
Sensory Perception: Expression and translocation of olfactory receptors
Gene Ontology:
Molecular function: odorant binding; olfactory receptor activity; G protein-coupled receptor activity
Biological process: sensory perception of smell; detection of chemical stimulus involved in sensory perception of smell; G protein-coupled receptor signaling pathway
Cellular component: plasma membrane; membrane
Genetic constraint (gnomAD): Missense variants: 387 observed, 354.31 expected, observed/expected ratio (o/e) 1.09, 90% interval 1 to 1.19. Synonymous variants: 149 observed, 124.21 expected, observed/expected ratio (o/e) 1.2, 90% interval 1.05 to 1.37.
Homologues: Orthologues: chimpanzee OR5H15 (96% identical), dog OR5H13 (75% identical), mouse Or5h26 (73% identical), dog OR5H16 (73% identical), mouse Or5h17 (73% identical), mouse Or5h19 (73% identical), rat Or5h26 (73% identical), rat Or5h17 (73% identical), rat Or5h17c (73% identical), dog OR5H12 (73% identical), rat Or5h17b (72% identical), dog OR5H11 (72% identical), and 13 more. Paralogues in human: OR5H1 (95% identical), OR5H14 (85% identical), OR5H6 (80% identical), OR5H2 (78% identical), OR5H8 (65% identical), OR5AC2 (58% identical), OR5K4 (51% identical), OR5K1 (50% identical), OR5K2 (49% identical), OR5K3 (48% identical), OR9G4 (47% identical), OR5B12 (46% identical), and 84 more.